ODC1 (ornithine decarboxylase 1)
Description:
Catalyzes the first and rate-limiting step of polyamine biosynthesis that converts ornithine into putrescine, which is the precursor for the polyamines, spermidine and spermine. Polyamines are essential for cell proliferation and are implicated in cellular processes, ranging from DNA replication to apoptosis.
Synonyms: ODC; BABS; NEDBA; NEDBIA
Tractability: Small molecule: an approved drug acts on it; a structure with a bound ligand is known; a high-quality ligand is known; it has a high-quality binding pocket; it belongs to a druggable protein family. PROTAC: ubiquitination databases record sites on it; a small molecule that binds it is known.
Target class: Enzyme; Lyase
Gene: Protein-coding gene on chromosome 2 (10,439,968 to 10,450,116, reverse strand). Ensembl gene ENSG00000115758.
Subcellular location (Human Protein Atlas): Golgi apparatus; Cytosol
Pathways (Reactome):
Metabolism: Metabolism of polyamines; Regulation of ornithine decarboxylase (ODC)
Gene Ontology:
Molecular function: ornithine decarboxylase activator activity; ornithine decarboxylase activity; protein binding; protein homodimerization activity; catalytic activity
Biological process: response to virus; polyamine metabolic process; putrescine biosynthetic process; regulation of protein catabolic process; polyamine biosynthetic process; spermidine biosynthetic process; spermine biosynthetic process
Cellular component: cytoplasm; cytosol
Genetic constraint (gnomAD): Loss-of-function variants: 18 observed, 43.23 expected, observed/expected ratio (o/e) 0.42, 90% interval 0.29 to 0.62. The upper end of that interval is the gene's LOEUF score, 0.62, which puts it in group 2 of 6, group 1 being the genes least tolerant of losing a copy. Missense variants: 494 observed, 611.73 expected, observed/expected ratio (o/e) 0.81, 90% interval 0.75 to 0.87. Synonymous variants: 214 observed, 219.93 expected, observed/expected ratio (o/e) 0.97, 90% interval 0.87 to 1.09.
Homologues: Orthologues: chimpanzee ODC1 (99% identical), macaque ODC1 (98% identical), dog ODC1 (95% identical), pig ODC1 (93% identical), rat Odc1 (92% identical), rabbit ODC1 (91% identical), mouse Odc1 (91% identical), guinea pig ODC1 (89% identical), tropical clawed frog odc1 (80% identical), zebrafish odc1 (74% identical), Drosophila melanogaster Odc1 (38% identical), Drosophila melanogaster Odc2 (36% identical), and 1 more. Paralogues in human: AZIN2 (51% identical), AZIN1 (49% identical).
Diseases named in the same sentence as ODC1 in open-access papers:
ODC1 is named in the same sentence as 145 diseases in open-access papers, as found by Europe PMC text mining. Sharing a sentence is not in itself a finding about the gene and the disease. The quoted sentences say what the papers report.
neuroblastoma (40 papers, 2006 to 2025). Neuroblastoma (NB) is the most common solid, extracranial childhood tumor. "Among other polyamine biosynthesis-related genes, ODC1, the rate-limiting enzyme in polyamine synthesis, is critically associated with the oncogenesis of diffuse intrinsic pontine glioma and neuroblastoma and is therefore a potential therapeutic target." (PMID 40761256, 2025). "We assessed DFMO PK for comparison with plasma concentrations achieved in preclinical mouse models that demonstrate anti-neuroblastoma efficacy, ODC1 functional polymorphisms, and preliminary anti-tumor activity for this combination." (PMID 38200233, 2024). "MYCN was a stronger transcriptional regulator of the ODC1 promoter containing the G allele, and preferentially bound the G allele over the A. Two neuroblastoma cohorts were used to investigate the clinical impact of the SNP." (PMID 33918978, 2021). "We have shown that the ODC1 G316A polymorphism is functionally important in childhood neuroblastoma." (PMID 33918978, 2021). "We showed that this variant impacts the ability of MYCN to regulate ODC1, and that it also influences outcome in neuroblastoma, with the rarer variant associated with a better survival." (PMID 33918978, 2021). "Despite the differing role of ODC1 in neuroblastoma, these findings are consistent with our observations that the A allele is linked to lower ODC1 expression." (PMID 33918978, 2021). "We demonstrate that the ODC1 G316A polymorphism influences ODC1 expression, neuroblastoma cell growth and response to DFMO." (PMID 33918978, 2021). "We have demonstrated that the ODC1 G316A polymorphism has functional significance in neuroblastoma and is subject to allele-specific regulation by the MYCN oncoprotein." (PMID 33918978, 2021). "Together these observations suggest that the A allele variant reduces ODC1 transcription, thereby moderating neuroblastoma cell proliferation and influencing response to DFMO-based therapies." (PMID 33918978, 2021). "Here we studied a naturally occurring genetic variant or polymorphism that occurs in the ODC1 gene, and used gene editing to demonstrate the functional importance of this variant in terms of ODC1 levels and growth of neuroblastoma cells." (PMID 33918978, 2021). "High ODC1 expression is found in MYCN-amplified neuroblastoma and is associated with a poor prognosis." (PMID 33918978, 2021). "ODC1 has been identified as a genetic marker for colon cancer and over-expression of ODC1 has been linked to high risk neuroblastomas and colorectal and breast cancers." (PMID 24386364, 2013). "ODC1 is a well-established oncogene in its own right, with high ODC1 activity associated with tumor growth in several human cancers, including neuroblastoma." (PMID 23181218, 2012). "In neuroblastoma there is significant evidence that ODC1 is overexpressed in high risk disease." (PMID 23181218, 2012). "The MYCN‐polyamine axis is of particular significance in neuroblastoma research, since multiple genes within the polyamine pathway, including ODC1 and SLC3A2, are direct targets of MYCN." (PMID 39981745, 2025). "When DFMO was combined with a polyamine transport inhibitor, AMXT 1501, to further address resistance to ODC1 inhibition, this combination resulted in the decreased growth of neuroblastoma cell lines in vitro and in vivo for TH-MYCN transgenic mice." (PMID 40004600, 2025). "It is well‐established that ODC1‐mediated polyamine biosynthesis is one of the mechanisms by which MYCN amplification drives neuroblastoma tumor cell proliferation." (PMID 39981745, 2025). "Neuroblastoma is characterized by increased levels of intracellular polyamines, as well as elevated expression of ornithine decarboxylase 1 (ODC1), the rate limiting enzyme in the de novo polyamine synthesis pathway, which is predictive of poor outcome." (PMID 39981745, 2025).
neuroblastoma (continued). "A study that has been discussed already has observed that ODC1 expression is significantly higher in MYCN-positive neuroblastomas and there was a strong significant correlation between MYCN expression and ODC1 expression (r=0.80, p<0.0001)." (PMID 37206500, 2023). "One of the most important conclusions from the study was that ODC1 expression correlates with survival in neuroblastoma." (PMID 37206500, 2023). "While the patient samples in our study cohort that expressed the highest levels of ODC1 transcript exhibited a GG genotype, we were unable to show a significant difference in ODC1 expression level in the neuroblastoma cohorts split by genotype." (PMID 33918978, 2021). "Mounting studies reported that ODC1 expression was increased in many cancers, such as esophageal carcinoma, colorectal cancer, hepatocellular carcinoma, neuroblastoma, and ovarian cancer." (PMID 34804983, 2021). "Further, the rate-limiting enzyme of polyamine synthesis ODC-1 is a direct downstream target of MYCN (and c-MYC), directly linking deregulation of polyamine metabolism to high-risk neuroblastoma, often characterized by MYCN amplification (reviewed in66)." (PMID 29968769, 2018). "Of note, ODC1 which is located within 5 Mb of MYCN is co-amplified with MYCN in 15–20% of MYCN-amplified neuroblastomas and ODC1 is significantly overexpressed in those tumors, thus presenting the first example of oncogene-target gene co-amplification." (PMID 29240775, 2017). "MYCN was later described as an important regulator of ODC1 in neuroblastoma." (PMID 40004600, 2025). "Furthermore, c‐MYC also binds the ATP13A3 and ODC1 promoter in neuroblastoma cells, albeit at a different region than MYCN, potentially denoting differences in MYCN and c‐MYC‐mediated regulation of expression." (PMID 39981745, 2025). "ODC1 is a direct target of MYC proteins and is associated with poor survival in neuroblastoma." (PMID 37760568, 2023). "Overall, these data are in contrast with the neuroblastoma results and suggest a unique biology for this MYCN-driven pediatric malignancy where the AA genotype predicts a better outcome and where high ODC1 expression is consistently associated with poor outcome." (PMID 33918978, 2021). "It is therefore possible that the differential SNP effects in the adult cancers, by comparison with neuroblastoma, may be due to differential expression of some of these ODC1-regulating TFs." (PMID 33918978, 2021). "The literature surrounding breast and colorectal cancer prognosis in relation to ODC1 expression is not conclusive, whereas in neuroblastoma it is well established that high ODC1 mRNA expression is associated with poor outcome." (PMID 33918978, 2021). "Neuroblastomas are reliant on high levels of cellular components called polyamines for their growth and malignant behavior, and the gene regulating polyamine synthesis is called ODC1." (PMID 33918978, 2021). "Elevated ATP13A3 expression in neuroblastoma patients is associated with worse survival, which suggests that ATP13A3‐mediated polyamine uptake may contribute to malignant neuroblastoma phenotypes, similar to ODC1‐mediated polyamine biosynthesis." (PMID 39981745, 2025). "Therefore, the impact of the genotype on ODC1 expression in neuroblastoma may depend on the balance of MYCN levels and MAD1/MXI1 levels, and their binding with MAX." (PMID 33918978, 2021). "In neuroblastoma, the expression levels of MYCN are strongly correlated with those of ODC1, and high levels of ODC1 driven by MYCN amplification and overexpression are strongly associated with poor clinical outcome in NB patients." (PMID 33628735, 2020). "However, while the polyamine synthesis inhibitor DFMO, which targets ODC1, appeared promising in reducing relapse and increasing overall survival time as maintenance therapy for high‐risk neuroblastoma in remission, it was not very effective in the relapsed setting." (PMID 39981745, 2025).
neuroblastoma (continued). "Our analysis suggests that ATP13A3 is a MYC target gene like ODC1 and SLC3A2 and that high expression of ATP13A3 represents an independent prognostic predictor of poor outcome in neuroblastoma." (PMID 39981745, 2025). "Known neuroblastoma-related genes such as MYCN, TERT, ODC1, CDK4, and MDM2 were recurrently affected by different classes of complex rearrangements including ecDNA, chromothripsis, and CnCs." (PMID 37868040, 2023). "Eventually, several laboratory studies showed a direct and statistically significant relationship between ornithine decarboxylase (ODC1) and MYCN gene expression, which led to the exploration of newer avenues for the use of DFMO - especially in neuroblastoma." (PMID 37206500, 2023). "Transgenic mice used in a preclinical study that used polyamine antagonist regimens targeting ODC1 and SAMDC had their neuroblastoma initiation reduced." (PMID 36551330, 2022). "The ODC1 and other polyamine enzyme genes are dysregulated in MYC-amplified tumors such as neuroblastomas." (PMID 33806076, 2021). "Our results show that the A and G alleles of the ODC1 G316A promoter SNP differentially affect ODC1 expression, as well as MYCN-mediated ODC1 transactivation of the E-box region and MYCN oncogenic processes in neuroblastoma cells in vitro." (PMID 33918978, 2021). "Ornithine decarboxylase (ODC1), the rate-limiting enzyme in polyamine synthesis, is frequently deregulated in neuroblastoma tumors and represents another potential therapeutic target." (PMID 30384486, 2018). "In neuroblastoma, the polyamine regulating ODC1 was found co-upregulated with MYCN and correlates with poor outcome in neuroblastoma, suggesting a detrimental role in neuroblastoma biology." (PMID 29947893, 2018). "The gene expressing ODC, ODC1, is activated by N-MYC and is upregulated in MYCN-amplified human neuroblastomas." (PMID 26771642, 2016). "ODC1, an oncogenic MYCN target, is rate-limiting for polyamine synthesis, and is overexpressed in many cancers including neuroblastoma." (PMID 23181218, 2012). "AMD1 has been shown to be up-regulated following ODC1 inhibition and it has been reported that combined DFMO and SAM486A therapy is synergistic in neuroblastoma." (PMID 23181218, 2012). "Since MYCN may have a stronger impact on the transcriptional regulation of ODC1 than of ATP13A3, neuroblastoma cells may be more dependent on biosynthesis and less dependent on polyamine uptake when MYCN is expressed." (PMID 39981745, 2025). "Furthermore, some investigators found that the inhibition of ODC1, a direct target of MYCN, inhibited neuroblastoma cell proliferation, prevented spontaneous tumourigenesis in mice, and enhanced the antitumour efficacy of conventional cytotoxicity." (PMID 37461251, 2023). "When DFMO was added to neuroblastoma cell lines as a part of the same study, there was growth inhibition mediated by ODC1 suppression and was observed in cells independent of MYCN amplification." (PMID 37206500, 2023). "Interestingly, upon examination of other known ODC1 transcriptional regulators, we found that CREB1 was expressed at higher levels in neuroblastoma compared to other adult tumor types, whereas WT1 was expressed at lower levels." (PMID 33918978, 2021). "Ornithine decarboxylase (ODC1), a critical regulatory enzyme in polyamine biosynthesis, is a direct transcriptional target of MYCN, amplification of which is a powerful marker of aggressive neuroblastoma." (PMID 33918978, 2021). "Collectively, our data is the first to report that the CDC27/ODC1 axis promotes tumorigenesis and acts as a positive regulator of ferroptosis in NB, highlighting that CDC27 may represent a novel therapeutic strategy and prognostic biomarker in neuroblastoma." (PMID 35242701, 2022). "However, high ODC1 expression also predicts poor outcome in MYCN non-amplified neuroblastoma suggesting it has oncogenic abilities independent of MYCN." (PMID 33918978, 2021).
colon carcinoma (16 papers, 2013 to 2024). "Further studies should explore the association among ODC1, and colon cancer." (PMID 36944972, 2023). "Interestingly, we observed a potential site-specific association for decrease in colon cancer risk in the presence of ODC1’s rs2302615 A allele." (PMID 29425227, 2018). "A single nucleotide polymorphism in the E-box region of the ODC1 gene affects the binding of MYC and MAD to ODC1 and is related to the recurrence of colon cancer." (PMID 33292222, 2020). "Neither of these studies addressed whether ODC1 expression is directly altered by the SNP, although it is known that ODC1 levels are certainly increased compared to normal tissues in both breast and colon cancer." (PMID 33918978, 2021). "In summary, our results suggest variant alleles of the genes involved in aspirin pathways, CYP2C9, ODC1 and UGT1A6, may be involved in the modification of CRC or colon cancer risk independently or in conjunction with aspirin use." (PMID 29425227, 2018). "Site-specific meta-analysis of colon and rectum showed approximately 20% decrease in colon cancer risk only in the presence of CYP2C9 rs1799853 variant allele (OR = 0.79, 95% CI = 0.65–0.95, P = 0.01, I2 = 0) and ODC1 rs2302615 variant allele (OR = 0.80, 95% CI = 0.69–0.93, P = 0.004, I2 = 0)." (PMID 29425227, 2018). "We discovered new colon cancer related genes including AC007952.4, NEK8, CHRM3, ANO7, B3GNT6, NEURL1, ODC1 and KCNMA1." (PMID 36944972, 2023). "Coupled this with the observation suggesting preferential binding of MAD1 to ODC1 promoter containing A allele in two colon cancer cell lines- HT29 and HCT116, it is likely that the carriers of rs2302615’s variant allele may observe reduced risk of developing colon cancer." (PMID 29425227, 2018).
prostate carcinoma (15 papers, 2010 to 2026). A carcinoma that arises from epithelial cells of the prostate gland. "ODC1 dysregulation has been associated with liver cancer and prostate cancer, and several studies have reported changes in the transcription, translation and degradation of ODC1 during carcinogenesis." (PMID 38216963, 2024). "The IPA demonstrated that important biochemical molecules such as VEGF, ERK1/2, p38 MAPK and PLA2G7, NADPH oxidase, SMAD3 and ODC1 were involved in the biological network associated with berberine against prostate cancer." (PMID 29029409, 2017). "Although ODC1 is known to be involved in prostate cancer development, exactly how it drives the disease mechanistically is not fully understood." (PMID 41803527, 2026). "To explore this, we created a prostate cancer cell model with reduced ODC1 expression and examined its effects on tumour behaviours." (PMID 41803527, 2026). "By contrast, the androgen receptor typically acts in prostate cancer to upregulate ODC1 expression, and indeed ODC1 overexpression alone may be enough to drive prostate tumorigenesis." (PMID 36551330, 2022). "BTF3, HINT1, NDRG1 and ODC1 could be developed as epithelial specific biomarkers for tissue based diagnosis and stratification of prostate cancer." (PMID 24386364, 2013). "We used quantitative immunohistochemistry to show that the expression of BTF3, HINT1, NDRG1 and ODC1 proteins is increased in prostate cancer tissue and could serve as putative targets for the investigation of carcinogenesis or biomarkers for disease." (PMID 24386364, 2013). "We chose four genes BTF3, NDRG1, HINT1 and ODC1 that are up-regulated in prostate carcinoma (oncomine.org; selection criteria: p=0.0001, 2 fold change and in top 10% of genes over-expressed in the overall dataset) in at least four normal vs cancer prostate gene expression analysis datasets." (PMID 24386364, 2013).
breast carcinoma (13 papers, 2005 to 2024). "Microarray and clinical data from 1372 breast cancer patients who received chemotherapy revealed that mRNA levels of ODC1 or SRM above the median were associated with decreased RFS." (PMID 39058337, 2024). "Co‐administration of difluoromethylornithine (DFMO), a specific inhibitor for ODC1 also significantly blocked paclitaxel‐induced enrichment of ALDH+ cells in breast cancer cells." (PMID 39058337, 2024). "Moreover, ODC1 is overexpressed in several human cancers such as colon, liver, and breast carcinomas." (PMID 32610656, 2020). "Indeed, RPPA data revealed an enrichment of cell cycle‐related genes including CDC25C and PLK1 in proteins downregulated by metformin, echoing a previous report showing selective translational inhibition of cell cycle regulators such as cyclin E2 and ODC1 by metformin in breast cancer cells." (PMID 30221473, 2018). "Whether increased ODC1 levels in LCC9 xenografts treated with CB-839 and everolimus reflect a disruption of the polyamine pathway, which is known to promote breast cancer cells growth, remains to be clarified." (PMID 31428575, 2019). "Paclitaxel treatment elevated intracellular levels of ornithine and total polyamine (including putrescine, spermidine, and spermine), and increased expression of ODC1 and SRM (but not SMS) in breast cancer cell lines." (PMID 39058337, 2024).